TNF (tumor necrosis factor)
Diseases named in the same sentence as TNF in open-access papers (continued):
Sharing a sentence is not in itself a finding about the gene and the disease.
acute appendicitis (12 papers, 2015 to 2025). "Previous studies have demonstrated the positive association of TNF-α with complicated appendicitis, distinguishing it from uncomplicated cases." (PMID 40150581, 2025). "TNF-α is also a potent proinflammatory mediator that has been associated with complicated acute appendicitis as well as local ischaemia." (PMID 34392384, 2021). "The increased TNFα expression is associated with fever and loss of appetite, which are also found in acute appendicitis." (PMID 33224488, 2020). "Children with complicated acute appendicitis had considerably higher serum TNF-α levels compared to those with uncomplicated appendicitis, according to two investigations conducted on children with AA." (PMID 40150581, 2025). "The aim of this study was to investigate the immunohistochemical expression of TNF-α, IL-6, IL-2R and serotonin in appendices resected from adult patients with symptoms of acute appendicitis, including those with histologically normal appendices." (PMID 34392384, 2021). "Gene analysis has shown that expression of TNF-α, IL-12, interferon-γ, IL-4, IL-2 and IL-15 in samples of acute appendicitis differed when compared with controls." (PMID 34392384, 2021). "Serum IL-10 and IL-6 were significantly elevated at presentation, and IL-6, IL-8 and TNF-α levels were higher in complicated appendicitis." (PMID 33060696, 2020). "Similar to our findings in appendicitis, a comparable result for TNF-α was found in a previously reported study." (PMID 32953890, 2020). "At presentation, serum IL-6, IL-8 and TNF-α levels were significantly higher in complicated versus uncomplicated appendicitis patients." (PMID 33060696, 2020). "Research has demonstrated that probiotics can decrease the levels of pro-inflammatory cytokines and chemokines, such as tumor necrosis factor-alpha (TNF-alpha) and interleukin-6 (IL-6), which are typically elevated in acute appendicitis." (PMID 37514986, 2023). "Serum IL-6 and TNF-α levels in the PA group were higher than those in the non-perforated appendicitis group." (PMID 38892260, 2024). "However, as the differences in TNF-α expression between complicated and uncomplicated acute appendicitis samples were not statistically significant it could be acting synergistically with other cytokines in the development of complicated acute appendicitis." (PMID 34392384, 2021).
atopic asthma (12 papers, 2010 to 2024). An asthma that is characterized by symptoms that are triggered by an allergic reaction caused by inhaled allergens such as dust mite allergen, pet dander, pollen and mold. "Using the cis-pQTL instrument definition, an inverse association was found between genetically proxied concentrations of tumor necrosis factor-alfa (TNF-a) and risk of atopic asthma (OR: 0.38, 95%CI: 0.26 to 0.54, p = 9.78 × 10−8) (FDR<5%)." (PMID 39319267, 2024). "TNF-α is a member of the TNF gene superfamily located within the human major histocompatibility complex on chromosome 6p, linked to atopic asthma in several studies." (PMID 25759826, 2014). "When subgroup analysis was performed according to atopic status, significant association was observed between this polymorphism and atopic asthma risk, suggesting that the TNF-α rs1800629 polymorphism may play a role in the etiology of atopic asthma." (PMID 24936650, 2014). "In regard to IgE-induced chronic inflammation in atopic asthma it would be of interest if the presence of IgE increases the sensitivity of tissue forming cells to other remodeling relevant proteins such as tumor growth factor-β or tumor necrosis factor-α." (PMID 26332463, 2015). "However, in obese mice genetically deficient in TNF-α, the severity of increases in airway responsiveness induced by O3 were enhanced, which implies a protective effect of TNF-α in this animal model of non-atopic asthma." (PMID 38878250, 2024). "Hypermethylated tumor necrosis factor (TNF) and human leukocyte antigen (HLA)-DPA1 are also reportedly correlated with immune response in childhood atopic asthma." (PMID 36118895, 2022). "In this study intracellular cytokine expression of IL-2, IL-4, IL-10, IL-13, IFN-γ, and TNF-α in CD4+ and CD8+ T cells in children with atopic asthma were measured by flow cytometry." (PMID 21197090, 2010). "In that report, PBMCs of atopic asthma patients carrying −2192C showed increased expression of TLR1 mRNA and protein, increased production of proinflammatory cytokine TNF-α and TH1 cytokines IL-12 and IFN-γ, and decreased production of TH2 cytokine IL-4 after stimulation with TLR1/2 ligand Pam3CSK4." (PMID 27727278, 2016). "Another study in children with atopic asthma showed an increase in the percentage of CD4 and CD8 cells producing IL-4 and a decrease in CD4 cells producing IFNγ in comparison with healthy controls, while the percentage of cells producing TNF remained unchanged." (PMID 27799958, 2016).
Blau syndrome (12 papers, 2014 to 2024). Blau syndrome (BS) is a rare systemic inflammatory disease characterized by early onset granulomatous arthritis, uveitis and skin rash. "This study demonstrated that abnormal cytokine expression in macrophages from untreated patients requires IFNγ stimulation, and that anti-TNF treatment corrects the abnormalities associated with Blau syndrome, even in the presence of IFNγ." (PMID 35711422, 2022). "Apart from glucocorticoids, TNF blockers are the most effective drugs in controlling disease activity in Blau syndrome." (PMID 38984133, 2024). "Analysis of the clinical data of Blau syndrome patients in Japan showed that of the 26 patients treated with anti-TNF agents, only one was blind, and the blindness happened before the administration of biologics." (PMID 36915122, 2023). "Next, we tried to clarify how anti-TNF treatment helps to control inflammation by comparing characteristics such as transcriptome profiling and cytokine secretion by MDMs from untreated and anti-TNF-treated Blau syndrome patients." (PMID 35603217, 2022). "While several new therapies have been reported, including JAK inhibitors, anti-IL-6 and anti-IL-1 therapies, anti-TNF therapy plays a central role in the treatment of Blau syndrome." (PMID 35711422, 2022). "Although the expression of both TNFα and IFNγ in the lesional skin of a Blau syndrome patient was previously reported, the genetic background of the patient was not clarified." (PMID 33923123, 2021). "An investigation into the cellular phenotypes of Blau syndrome may be necessary to evaluate the efficacy of anti-TNF therapy since the pharmacological mechanism behind their effectiveness in Blau syndrome is unknown." (PMID 35711422, 2022). "Therefore, although the molecular mechanisms by which the genetic mutations in NOD2 lead to granuloma formation remain unclear, it is possible that prior exposure to TNFα combined with IFNγ stimulation may provide the impetus for the clinical manifestations of Blau syndrome." (PMID 35711422, 2022). "For Blau syndrome, DADA2 and HA20 patients, we initiated anti-TNF-α therapies and have observed some good responses." (PMID 33042144, 2020). "Macrophages, differentiated from the peripheral blood of Blau syndrome who did not receive anti-TNF treatment, released inflammatory cytokines after being primed with IFNγ." (PMID 35711422, 2022).
bronchopulmonary dysplasia (12 papers, 2014 to 2025). Bronchopulmonary dysplasia is a chronic respiratory disease that results from complications related to lung injury during the treatment of infant acute respiratory distress syndrome in low-birth-weight premature infants or from abnormal lung development in older infants. "Exposure to or infusion of IL-1β and TNF-α caused the defects associated with peripartum intrauterine inflammation, abnormal lung development associated with bronchopulmonary dysplasia, and brain injury." (PMID 37099541, 2023). "They finally concluded that the adenine allele of TNF-α238 may reduce the risk and severity of bronchopulmonary dysplasia." (PMID 28298812, 2017). "However, the AA and GA TNF-α238 genotypes were much less likely to occur among infants with bronchopulmonary dysplasia than among healthy infants." (PMID 28298812, 2017). "The adenine allele of TNF-α238 was absent among infants with severe bronchopulmonary dysplasia and occurred significantly less often among infants with moderate or severe bronchopulmonary dysplasia, compared with infants with mild bronchopulmonary dysplasia." (PMID 28298812, 2017). "As a therapeutic tool, caffeine is used to treat apnea of prematurity in preterm newborn infants, and it has been found to reduce bronchopulmonary dysplasia (BPD), a chronic lung disease of preterm infants, by reducing pulmonary inflammation, including IL-6 and TNF-α secretion." (PMID 34371919, 2021). "Besides, mechanical ventilation can lead to bronchopulmonary dysplasia in TNF-α-knockout mice by inducing the transforming growth factor (TGF) signaling pathway, indicating that the balance between TNF-α and TGF signaling is essential for airway development." (PMID 34395451, 2021).
colonic disease (12 papers, 2012 to 2025). "Previous study confirmed that rutaecarpine and TNF-α exert activity in colon diseases, and our study suggested TNF-α was proposed to be directly related to Evodia rutaecarpa." (PMID 38041080, 2023). "At the time of diagnosis the patient had ileal disease with a mixed inflammatory infiltrate and cryptitis which, in contrast to the colonic disease, had strongly diminished after intensive treatment with prednisolone, azathioprine, and anti-TNF." (PMID 34226674, 2021). "All phenotypes demonstrated impaired TNF release, with the greatest defect in patients with colonic disease." (PMID 22434667, 2012). "Furthermore, an association with disease localisation in patients with CD was seen e.g. patients with colonic disease (L2) had significant lower TNF-α production upon LPS stimulation compared to patients with only ileal disease (L1)." (PMID 26208333, 2015).
coronary artery aneurysms (12 papers, 2009 to 2025). "Serum TNF levels are elevated in patients with KD and have been associated with IVIg failure and increased risk for coronary artery aneurysms." (PMID 31775898, 2019). "Type I interferon augments TNF- and IL-1β-mediated inflammatory responses and is elevated in KD with coronary artery aneurysms." (PMID 41394864, 2025). "A previous study has shown that TNF-α is crucial for the development of coronary aneurysms in KD patients." (PMID 27800490, 2016). "Actually, blockage of TNF-α has been shown to inhibit the development of coronary aneurysms in LCWE-injected mice." (PMID 27800490, 2016). "While KD involves chronic endothelial activation and a significant risk of coronary aneurysms, MIS-C is characterized by acute elevations in proinflammatory cytokines—such as IL-6, IL-1β, and TNF-α—leading to systemic inflammation and transient cardiac dysfunction." (PMID 40332089, 2025). "In addition, serum TNF-α level in KD patient is significantly increased, and TNF-α plays a promoting role in inducing coronary artery inflammation and the occurrence of coronary artery aneurysms." (PMID 39268468, 2024). "Furthermore, serum TNF-α levels are significantly elevated in children with acute KD, and they correlate with the incidence of coronary artery aneurysms." (PMID 35052869, 2022). "TNF-α is elevated in the acute phase of KD and may be a contributing factor in patients who subsequently develop a coronary artery aneurysm." (PMID 31101091, 2019). "Moreover, TNF antagonists are an important treatment for Kawasaki patients also suffering from acute vasculitis and coronary artery aneurysms." (PMID 19582157, 2009). "A cytokine storm including tumor necrosis factor (TNF)-α, IL-6, and granulocyte colony-stimulating factor is evident in patients in whom coronary artery aneurysms are developing." (PMID 30547812, 2018). "Others have found that serum levels of sIL-2R and TNF-α were significantly higher in the patients with coronary aneurysm than in those without." (PMID 30611297, 2019). "Furthermore, interleukin (IL)-6 and tumor necrosis factor-α levels were also significantly higher in KD patients with coronary aneurysm compared to those without coronary aneurysm." (PMID 22577247, 2012).
Cryptococcal meningitis (12 papers, 2015 to 2025). Meningeal inflammation produced by cryptococcus neoformans, an encapsulated yeast that tends to infect individuals with acquired immunodeficiency syndrome and other immunocompromised states. "18-week survival after diagnosis of cryptococcal meningitis was associated with higher CSF leukocytes at baseline with greater T helper 1 (IFN-γ, IL-2 and TNF-α cytokines), T helper 17 (IL-17A cytokine) and CXCR3+ T cell (CXCL10 chemokine) responses." (PMID 39928682, 2025). "HIV-infected patients are known to present lower Th2 cytokines levels than healthy subjects, and this is associated with Pneumocystis pneumonia, and the impairment of tumor necrosis factor-α (TNF-α) and interferon-γ in response to cryptococcal meningitis." (PMID 32944157, 2020). "TNF-α and type I interferons (IFNs), such as IFN-β, have been implicated in the control of cryptococcal meningitis in mice and humans." (PMID 28143979, 2017). "Given the positive correlation association of the CSF leukocytes and measured CSF protein and cytokine levels, the CSF leukocytes and other neuroimmune activated cells are the likely source of immune modulating IL-17A and Th1 cytokine; TNF-α cytokine factors in CSF with cryptococcal meningitis." (PMID 39928682, 2025). "Moreover, lenalidomide induces a sustained decrease in plasma IL-6, TNF-α, CRP, D-dimer, and CA-HIV-1 RNA from PBMCs in patients with HIV-associated cryptococcal meningitis." (PMID 35967862, 2022). "In a similar manner, subgroup analyses in HIV-associated cryptococcal meningitis suggested that the greatest benefit of a short-course IFNγ adjuvant therapy was gained among patients with a lack of Cryptococcus-specific IFNγ/TNF CD4+ T cell responses." (PMID 29375567, 2017). "Adding TNF-α or IFN-β to our assays, at levels comparable to those seen in HIV-positive (HIV+) patients with cryptococcal meningitis (24, –, 26), yielded small but significant changes in barrier permeability, consistent with those reports." (PMID 28143979, 2017). "For example, the HIV-infected individuals who were treated for cryptococcal meningitis and survived, had higher levels of several immune modulators in the CSF (IFNγ, TNF-α, IL-6 and IL-8) compared to those who did not." (PMID 29970809, 2018). "Low CSF concentrations of IFN-γ and a blood CD4+ T-cell phenotype characterized by a lack of IFN-γ and TNF-α production have been observed in HIV-infected individuals who died from cryptococcal meningitis." (PMID 26768248, 2016).
diphtheria (12 papers, 1996 to 2025). A Gram-positive bacterial infection caused by Corynebacterium diphtheriae. "After subcutaneous injection in patients, IM showed immunomodulatory effects, as manifested by decreasing levels of interleukin-6 (IL-6) and tumor necrosis factor (TNF) in response to diphtheria toxoid vaccination." (PMID 32585846, 2020). "The effect of vaccination with diphtheria toxoid (AD-M) on TNF and IL-6 production has been studied in humans." (PMID 18475748, 1996). "Mice which had received all three shots of Infanrix® IPV and were sacrificed 7 days after the third shot had significantly more diphtheria-specific CD4+ T cells producing IL-2, IL-6, or TNF-α when treated with GM-CSF than placebo-treated controls." (PMID 29961602, 2018).
Dyskinesia (12 papers, 2020 to 2025). A movement disorder which consists of effects including diminished voluntary movements and the presence of involuntary movements. "A normalization of the L-DOPA-induced expression of AMPA receptor subunit GluR1, which is modulated by TNF-α levels and contributes to the synaptic abnormalities underlying dyskinesia, was also observed in this study." (PMID 33854417, 2021). "At the same time, increased cytokines play a role in the dyskinesia that occurs in PD, and these are molecules such as TNF-α and IL-6." (PMID 40464816, 2025). "Highly enriched Alistipes has been shown to be positively correlated with the expression of TNF; elevated relative abundance of Bacteroides was also correlated with the elevated plasma TNF-α and dyskinesia in PD patients." (PMID 40426604, 2025). "Patients with dyskinesia exhibited notably higher IL-6 levels compared to controls, and TNF-α was significantly elevated in both PD patient groups relative to the control group." (PMID 38392998, 2024). "In our study, we detected significantly higher TNF-α concentrations in both the dyskinesia and non-dyskinesia PD groups compared to the control group." (PMID 38392998, 2024). "Recovery of dyskinesia in PD rats; reduction of TNF-α production in the brain substantia nigra region; prevention of BV-2 activation." (PMID 39149548, 2024). "The relationship between striatal TNF-α levels and dyskinesia is weaker, but the evidence for a pathogenetic role is stronger." (PMID 37810262, 2023). "In the mouse, however, a relationship does exist between severity of dyskinesia and expression of TNF and activation of microglia is also seen." (PMID 37810262, 2023). "In the present study, the serum level of TNF-α was significantly higher in the PD patients, both with and without dyskinesia compared to the control group, whereas progranulin was increased only in the PD non-dyskinesia patients." (PMID 38392998, 2024). "The inhibitory effects on TNF-α may be particularly important as this cytokine has the potential to stimulate the release of glutamate, a neurotransmitter crucially involved in dyskinesia." (PMID 36506543, 2022). "Increased release of TNF-α by lymphocytes stimulated by LPS may contribute to dyskinesia by promoting maladaptative synaptic plasticity in corticostriatal synapses." (PMID 34566874, 2021). "Still to better understand how TNF-α produced by astrocytes could be involved in L-DOPA-induced dyskinesia, we wished to evaluate the impact of this cytokine on the release of glutamate by cortical neurons in the presence or not of CPZ + CBD." (PMID 33510643, 2020). "We wished to determine whether the treatment with CPZ + CBD, reported being effective against dyskinesia, also had the capacity of reducing levels of TNF-α and IL-1β in the dorsal striatum of 6-OHDA-lesioned mice treated with L-DOPA." (PMID 33510643, 2020). "In preclinical studies, an increased production of proinflammatory cytokines such as TNF-α and IL-1β has been associated with a robust activation of glial cells in the DA-denervated striatum of 6-OHDA-infused hemi-parkinsonian rats that developed dyskinesia after L-DOPA treatment." (PMID 33854417, 2021). "To determine to what extent TNF-α released by activated astrocytes could contribute to dyskinesia in L-DOPA-treated mice, we measured levels of this cytokine in astrocyte cultures treated with glutamate (50 and 500 μM) for 24 h in the presence or not of CPZ + CBD (both at 0.1 μM)." (PMID 33510643, 2020). "L-DOPA is responsible of inducing dyskinesia (LID) in animals with partial lesion of SN, increasing plasmatic levels of TNFα and IL-1β, and treatment with CBD + CPZ lowered TNFα levels and ameliorated the LID and inflammatory prognostic of the model." (PMID 39533977, 2024).